ERCC2 (ERCC excision repair 2, TFIIH core complex helicase subunit)
Diseases named in the same sentence as ERCC2 in open-access papers (continued):
Sharing a sentence is not in itself a finding about the gene and the disease.
breast carcinoma (continued). "For heterozygous ERCC2 Lys751Gln, an increased risk for breast cancer was found with age at first OC use after 23 years." (PMID 18454848, 2008). "When age at first oral contraceptive use was after 23 years, a significant increase in breast cancer risk was obtained for heterozygous ERCC2 Lys751Gln (OR = 2.22; 95% CI = 1.15–4.29)." (PMID 18454848, 2008). "Heterozygous individuals for ERCC2 Asp312Asn which received a hormonal replacement therapy (HRT) exhibited a risk to develop breast cancer (OR = 1.39; 95% CI = 0.97–1.99)." (PMID 18454848, 2008). "Interestingly, ERCC2 variants and mutations have been associated with breast cancer risk or clinical responses in specific contexts." (PMID 29684080, 2018). "Besides, ERCC1 rs11615 (T allele), and ERCC2/XPD rs50872 (T allele) were associated with postmenopausal breast cancer, while XPC rs2228000 (T allele) was associated with premenopausal breast cancer." (PMID 27768589, 2016). "In addition, ERCC1 rs11615 carriers have a high risk of breast cancer with grade 3, while XPC rs2228000 and ERCC2/XPD rs50872 are linked to a high risk for breast cancer with grades 1 and 2, respectively." (PMID 27768589, 2016). "A trend to the increase in breast cancer risk could be observed with heterozygous women for the SNP at position 312 of ERCC2 protein (OR = 1.06; 95% CI = 0.93–1.21) after adjustment for age." (PMID 18454848, 2008). "In conclusion, we provide a useful resource on the mutational landscape of ERCC2 mutations in hereditary BC/OC patients and, as our key finding, we demonstrate the complexity of correct interpretation for the discovery of “bonafide” breast cancer susceptibility genes." (PMID 27504877, 2016). "In conclusion, we provide a useful resource on the mutational landscape of ERCC2 mutations in hereditary BC/OC patients and, as our key finding, we highlight the complexity of correct interpretation for the discovery of “bonafide” breast cancer susceptibility genes." (PMID 27504877, 2016). "The role of ERCC2-Lys751Gln polymorphisms and breast cancer development is still unknown." (PMID 24402573, 2014). "Perhaps further studies on the significance of ERCC2 variations in breast cancer patients will emerge in the future." (PMID 40994809, 2025). "For example, previous researches have displayed significant correlations between single nucleotide polymorphisms in ERCC2, ERCC3, and ERCC4 and the risk of developing lung, skin, and breast cancers." (PMID 39192988, 2024). "When missense variants were assessed, three further associations were observed for overall breast cancer (TMEM161A, SIPA1L1, ERCC2), and a further seven were observed for subtypes (RNF175, NCKAP1L, PHAX, SMARCA2, EML5, NTRK3, MED23)." (PMID 35884425, 2022). "Our results suggested that ERCC2-rs1799793 and MTHFR-rs1801133 represent suitable tool for assessing susceptibility to breast cancer in Moroccan population and prognosis." (PMID 29544444, 2018). "The purpose of this study was to explore the association of ERCC2 and MTHFR polymorphisms with genetic susceptibility to breast cancer in Moroccan population." (PMID 29544444, 2018). "They suggested that the variants of ERCC2, TLR4, IL-2, IL-6, and IL-21 genes had associations with breast cancer prognosis respectively." (PMID 25075970, 2014). "Details of genotype frequencies of the SNP rs13181 (ERCC2) among normal female and breast cancer subjects." (PMID 19615095, 2009). "The evidence supporting ERCC2 as a more penetrant breast cancer susceptibility gene, however, is not convincing." (PMID 35884425, 2022). "ERCC2-rs1799793-AA genotype correlated with ER+ and PR+ breast cancer." (PMID 29544444, 2018). "For tumor tissue characteristics, XPA rs1800975 and ERCC2/XPD rs50872 carriers have a high risk of breast cancer with negative expression of ER and PR." (PMID 27768589, 2016).
breast carcinoma (continued). "For the lymph node involvement subgroup, XPC rs2228001 and ERCC2/XPD rs50872 carriers have a high risk of breast cancer with negative lymph node involvement." (PMID 27768589, 2016). "Our results of cumulative analyses further emphasize the importance of changes that occur simultaneously in cellular transport (p.Ser893Ala/Thr in ABCB1, c.-24C>T in ABCC2) and DNA repair systems (p.Lys751Gln in ERCC2) for the outcome of treatment in breast cancer patients." (PMID 27527855, 2016). "Nonsmoker homozygous Asn at position 312 of ERCC2 tended towards an increase in the risk of developing breast cancer (OR = 1.4; 95% CI = 0.98–2.02)." (PMID 18454848, 2008). "There was modest evidence of an association with overall breast cancer risk for rare missense variants in three genes: TMEM161A (OR = 2.56 (CI 95% 1.19–5.51), p-value = 0.016), SIPA1L1 (OR = 1.68 (CI 95% 1.06–2.67), p-value = 0.026), and ERCC2 (OR = 1.45 (CI 95% 1.01–2.08), p-value = 0.047)." (PMID 35884425, 2022). "Similarly, ERCC1 and ERCC2 expression levels were significantly correlated (r = 0.61, p-value = 2 × 10−5, n = 75) in triple negative, but not correlated (r = − 0.10, p-value = 5 × 10−1, n = 68) in luminal A Breast cancer patients." (PMID 34837938, 2021). "Besides, homozygous Asn for ERCC2 312 tended to have an increase in breast cancer risk among nonsmokers, and a significant increase in breast cancer risk among OC users or with WHR > 0.85." (PMID 18454848, 2008). "A 2023 study in the US reported that breast cancer patients carrying three genes, BRCA1, BRCA2, and ERCC2, were up to 56% more likely to be diagnosed with SPNs." (PMID 40391756, 2025). "The best putative candidates in this group were TMEM161A, ERCC2, and SIPA1L1 for overall breast cancer, RNF175 and NCKAP1L for ER-positive disease, and PHAX, SMARCA2, NTRK3, EML5, and MED23 for ER-negative disease." (PMID 35884425, 2022). "Arguably, cancer-related effects of variations in ERCC2 may be influenced by variations in ERCC1, so both of the ERCC genes should be evaluated for genetic variation related to breast cancer." (PMID 19208188, 2009). "Differential reliance on the polymerase among pathways may help to explain why, e.g., in urothelial tumors carrying missense mutations in ERCC2, a key component of NER, the number of SBS5 mutations increases, while in breast cancer cell lines lacking the TLS polymerase REV1, it decreases." (PMID 40950171, 2025).
bladder cancer (40 papers, 2008 to 2025). "ERCC2 mutations have been associated with increased sensitivity to cisplatin-based chemotherapy in some bladder cancer cohorts, and functional analyses of selected ERCC2 mutations have demonstrated impaired NER activity." (PMID 40829180, 2025). "Our data demonstrate that clinically observed ERCC2 helicase-domain missense mutations strongly sensitize bladder cancer cells to cisplatin." (PMID 40829180, 2025). "To explore the clinical actionability of ERCC2 mutations, we assembled a multinational cohort of 2,012 individuals with bladder cancer and applied the highly quantitative CRISPR-Select assay to functionally profile recurrent ERCC2 mutations." (PMID 40829180, 2025). "SBS5, for instance, displays clock-like behavior, with mutation counts increasing with age, yet its mutational burden can vary in specific contexts, such as in bladder cancers with ERCC2 mutations and in cancers associated with tobacco smoking." (PMID 39778866, 2025). "The size of the cohort and the accompanying genomic, clinical, and novel functional data collected using CRISPR-Select has allowed us to comprehensively define frequencies and functional impacts of ERCC2 mutations in bladder cancer." (PMID 40829180, 2025). "In conclusion, our findings set the stage for integrated clinical interpretation of ERCC2 mutation status for optimized bladder cancer treatment." (PMID 40829180, 2025). "Taken together, these data demonstrate the utility of CRISPR-Select to define the functional impact of clinically observed ERCC2 mutations on bladder cancer cell fitness and cisplatin sensitivity." (PMID 40829180, 2025). "They found that ERCC2 mutations were independently associated with favourable prognosis in bladder cancer and it was a helpful clinical marker for risk stratification and treatment decisions." (PMID 40471489, 2025). "We recently identified a complex mutational signature, predominantly driven by the mutational signature SBS5 and ID8, that is significantly increased in NER deficient bladder cancer cases, especially those with ERCC2 mutations." (PMID 38589664, 2024). "It had been shown that mutations in ERCC2 were associated with the activities of COSMIC signature 5 in bladder cancer previously." (PMID 36495164, 2023). "Only one study has reported the presence of LOH in tumors from patients with ERCC2 germline mutations, and this has been found in bladder cancer patients carrying the p.Arg616Pro mutation in ERCC2." (PMID 38028607, 2023). "We showed that mutations in ERCC2 and other SMGs or pathways were associated with the activities of mutational signatures in bladder cancer." (PMID 36495164, 2023). "We also demonstrate that the specific mutational signatures associated with ERCC2 inactivation in bladder cancer are also present in a subset of ccRCC cases." (PMID 37996508, 2023). "In order to detect NER deficiency in clinical biopsies, we assessed whole exome sequencing data for the presence of an NER deficiency associated mutational signature previously identified in ERCC2 mutant bladder cancer." (PMID 37996508, 2023). "Somatic missense mutations in ERCC2 have emerged as clinically significant biomarkers for chemotherapy response in bladder cancer in several trials." (PMID 35813257, 2022).
bladder cancer (continued). "Among genes that are mutated less commonly in bladder cancer, noticeable are likely pathogenic mutations in the nucleotide excision repair helicase ERCC2, observed in three of the 10 cases with TMB above 30 mutations/MB." (PMID 35323317, 2022). "ERCC2 mutations were associated with shorter survival in colorectal and lung cancer, but were found to prolong survival in bladder cancer." (PMID 35444210, 2022). "Previous studies have shown that specific gene mutations are associated with higher platinum drug sensitivity in many cancers, such as CCDC69 mutation in ovarian cancer, ERCC2 mutation in bladder cancer, and BRCA mutation in pancreatic cancer." (PMID 35087829, 2021). "ERCC2 mutations indicate a better prognosis of chemotherapy for bladder cancer and a lower rate of recurrence and metastasis within 2 years." (PMID 34094968, 2021). "Next, we tested the association between mutations in the excision repair cross-complementing 2 (ERCC2) DNA repair gene and the cisplatin drug response in bladder cancer." (PMID 33127883, 2020). "For example, a recent microscopy-based nucleotide excision repair assay to profile ERCC2 mutations established a role for ERCC2 helicase domain mutations as a predictive biomarker in bladder cancer treated with cisplatin-based chemotherapy." (PMID 30885775, 2019). "In contrast to the sparce data on a possible role for IGFBP-2 in chemosensitivity of bladder cancer, there are convincing data indicating a role for ERCC2 mutations." (PMID 31903164, 2019). "According to the type of cancer, the ERCC2 polymorphism was associated with a significantly higher risk of bladder cancer." (PMID 28489582, 2017). "ERCC2 has also been linked to bladder cancer and a large meta-analysis completed in 2006 reported statistically significant associations between ERCC2 SNPs and skin, breast and lung cancer." (PMID 23637977, 2013). "To explore if ERCC2 helicase-domain mutations may predict cisplatin response in bladder cancer, we investigated the relationship between ERCC2 helicase-domain mutation status and patient outcomes in the assembled bladder cancer cohorts." (PMID 40829180, 2025). "This indicates that ERCC2 mutation status could be a very important biomarker for predicting the efficacy of NAC in bladder cancer patients and thus could direct the decision-making process regarding treatment, which may benefit the patient." (PMID 40471489, 2025). "The etiology of SBS5 is unknown but correlates with age and has been observed in human bladder cancers with mutation of the ERCC2 nucleotide excision repair enzyme and cancers due to tobacco smoking." (PMID 41353477, 2025). "It was possible that ERCC2 mutations may co‐operate with certain APOBEC enzymes to increase the mutagenicity of tumor cells during bladder cancer evolution." (PMID 36495164, 2023). "ERCC2 mutations in bladder cancer are linked with current smoking status." (PMID 35323317, 2022). "In fact, ERCC2 mutations could serve as a predictive biomarker for driving cisplatin responses that have been tested and validated in bladder cancers." (PMID 34966786, 2021). "Also, Qiang Li found that ERCC2 mutation can abrogate nuclear error repair in bladder cancer, thus increasing platinum drug sensitivity." (PMID 35087829, 2021). "Therefore, a unique relationship seems to exist between ERCC2 mutations and bladder cancer tumorigenesis, and additional work will be needed to define the molecular role of ERCC2 mutations as a bladder cancer driver." (PMID 28346378, 2017). "In addition to ERCC2, somatic alterations in other DNA damage and repair genes have been associated with improved response to DNA damage-based therapy in bladder cancer." (PMID 28346378, 2017). "Since Fhit is a genome caretaker protein, it is possible that its loss, which occurs frequently in bladder cancer, could predispose to the ERCC2 mutations associated with these cancers." (PMID 29254236, 2017).
bladder cancer (continued). "Interestingly, bladder cancer is the only solid tumor type identified to date in which ERCC2 is significantly mutated." (PMID 28346378, 2017). "Across three separate bladder cancer cohorts, ERCC2 was the only gene for which mutation status was significantly associated with signature 5 activity, suggesting that the spectrum of point mutations comprising signature 5 may represent the mutational effects of loss of normal NER function." (PMID 28346378, 2017). "Here, we assembled clinical and genomic data from patients with bladder cancer, which is, to our knowledge, the largest cohort of ERCC2-mutant bladder tumors characterized to date." (PMID 40829180, 2025). "In this study, we assembled the largest cohort of ERCC2-mutant bladder cancer cases analyzed to date." (PMID 40829180, 2025). "Subsequently, mRNA expression levels of ERCC2 and 5 were examined in bladder cancer tissues and normal bladder tissues." (PMID 39192988, 2024). "To address these questions, we conducted a multi-omics analysis using data from public databases and performed functional assays to validate the role of ERCC2 in bladder cancer." (PMID 39192988, 2024). "We also validated the role of ERCC2 in bladder cancer through in vitro assays, including CCK-8, colony formation, wound healing, and Transwell assays." (PMID 39192988, 2024). "To explore the effect of ERCC2 on bladder cancer T24 cells, we performed CCK-8 assay, colony formation assay, and three-dimensional multicellular spheres on the treated T24 cells." (PMID 39192988, 2024). "ERCC2 expression levels were significantly higher in bladder cancer than in its corresponding normal tissues." (PMID 39192988, 2024). "In our analysis, ID8 was present both in some of the ccRCC cell lines and patient biopsies at levels detected in ERCC2 mutant bladder cancer cases." (PMID 37996508, 2023). "ERCC2 is a protein participating in nucleotide excision repair (NER) and is mutated in a subset of hypermutated bladder carcinomas." (PMID 35323317, 2022). "We interpret these data to mean that damaging mutations in ERCC2 (XPD) contribute to conferring tumor advantage in patients with medium levels of mutational burden, particularly in those affected by carcinomas of the bladder, renal pelvis, and ureter." (PMID 34966786, 2021). "Among variants which were studied in association with bladder cancer we note Lys939Gln genotype (A > C; rs2228001) in XPC gene, Lys751Gln (rs13181) in ERCC2 gene and Asp1104His (G > C; rs17655) in ERCC5 gene." (PMID 21426550, 2011). "In this work, we have conducted a case-control study in order to assess the effect of tobacco and three genetic polymorphisms in XPC, ERCC2 and ERCC5 genes (rs2228001, rs13181 and rs17655) in bladder cancer development in Tunisia." (PMID 21426550, 2011). "The NER pathway has been reported to be the most significant modulator of bladder cancer risk and implicated many enzymes such as Xeroderma pigmentosum type C, D and G (XPC, ERCC2 and ERCC5)." (PMID 21426550, 2011). "Garcia-Closas evaluated the influence of common genetic variation in the NER pathway on bladder cancer risk by analyzing 22 single nucleotide polymorphisms (SNP) in seven NER genes (XPC, RAD23B, ERCC1, ERCC2, ERCC4, ERCC5, and ERCC6)." (PMID 19055767, 2008). "Assembly and characterization of a large multiinstitutional ERCC2-mutant bladder cancer cohort." (PMID 40829180, 2025). "Additionally, our in vitro assays showed that knockdown of ERCC2 expression inhibited the proliferation, migration, and invasion of bladder cancer cells." (PMID 39192988, 2024). "Through in-depth exploration of ERCC differential expression and its correlation with immune-related indicators, the unique microenvironment of tumors, and patient prognosis, we verified the potential role of ERCC2 in the process of bladder cancer genesis and progression." (PMID 39192988, 2024).